SOCS1 (suppressor of cytokine signaling 1)
Diseases named in the same sentence as SOCS1 in open-access papers (continued):
Sharing a sentence is not in itself a finding about the gene and the disease.
medulloblastoma (4 papers, 2013 to 2024). A malignant, invasive embryonal neoplasm arising from the cerebellum. "SOCS1 has recently been identified as direct transcriptional target of Hedgehog (Hh/GLI) signaling in human medulloblastoma cell lines, whereas silencing of SOCS1 promoted reduced medulloblastoma growth in vitro." (PMID 38711523, 2024). "Alternatively, it would be more convincing if the levels of SHP2, SOCS1/SOCS3 and/or PIAS3 are altered accordingly in medulloblastoma cells with suppressed STAT3 signaling." (PMID 28035977, 2016). "While in HaCaT cells induction of SOCS1 by GLI1 is moderate compared to GLI2act, strong expression of SOCS1 was found in the medulloblastoma cell line DAOY in response to either GLI1 or GLI2act expression." (PMID 24058673, 2013). "Here we show that SOCS1 is a direct target of Hh/GLI signaling in human keratinocytes and medulloblastoma cells." (PMID 24058673, 2013). "Upregulation of SOCS1 in response to Hh signaling is observed not only in HaCaT keratinocytes and DAOY medulloblastoma cells, but also in samples of human BCC." (PMID 24058673, 2013). "Here we show that SOCS1 is a direct target of Hh/GLI signaling in human keratinocytes and a medulloblastoma cell line." (PMID 24058673, 2013).
osteoporosis (4 papers, 2015 to 2025). A condition of reduced bone mass, with decreased cortical thickness and a decrease in the number and size of the trabeculae of cancellous bone (but normal chemical composition), resulting in increased fracture incidence. "The associations among SOCS1, AGO3, and the JAK2/STAT3 signaling pathway in osteoporosis progression were then evaluated." (PMID 41043430, 2025). "Herein, we identified bone marrow MSC (BMSC)-derived EVs harboring microRNA (miR)-29b-3p to regulate osteogenic differentiation through effects on the suppressor of cytokine signaling 1 (SOCS1)/nuclear factor (NF)-κB pathway via targeting of lysine demethylase 5A (KDM5A) in osteoporosis." (PMID 33553139, 2020). "Analysis of protein synthesis using the Western blot technique revealed comparable synthesis levels of fos-related antigen 1 (Fra1), suppressor of cytokine signaling 1 (SOCS1), and the TNF receptor-associated factor 6 (TRAF6) in the non-osteoporosis and osteoporosis groups for both cell types." (PMID 25563300, 2015).
parasite infection (4 papers, 2011 to 2018). "It is possible that parasite infection down-regulates the IFNγ-induced expression of phosphatases such as suppressor of cytokine signaling 1 (SOCS1), known to negatively regulate STAT1 signaling." (PMID 23527309, 2013). "The expression of different SOCS members in fish has been shown to be induced by viral, bacterial, and parasitic infection, and, in all the cases, SOCS1 and 3 expression is upregulated." (PMID 22203897, 2011). "In this case, blocking of SOCS1, a suppressor of cytokine signaling 1, expression resulted in high levels of type I IFN production, leading to increased IFN-γ production and reduced parasitemia, protecting mice from parasite burden-dependent death." (PMID 30619355, 2018).
scleritis (4 papers, 2016 to 2022). Inflammation of the sclera. "Of note, defective SOCS1 expression has been demonstrated in human scleritis patients." (PMID 35505065, 2022).
toxoplasmosis (4 papers, 2022 to 2024). A parasitic disease contracted by the ingestion or fetal transmission of toxoplasma gondii. "Toxoplasmosis promotes expression of anti-inflammatory responses such as suppressor of cytokine signaling 1(SOCS1), Arg1, TGF-β and IL-10, and also decreases the generation of inflammatory mediators including NO." (PMID 39840010, 2024). "In addition to the TNF pathway, we detected enrichment of candidate genes involved in the toxoplasmosis (TGFβ2/CHUK/CIITA/SOCS1) pathway in the tolerant animals." (PMID 35464478, 2022). "In addition, the TNF-signaling (bta04668; TRAF5/CREB5/CASP7/CHUK) and the toxoplasmosis (bta05145; TGFβ2/CHUK/CIITA/SOCS1) pathways were significantly enriched." (PMID 35464478, 2022).
triple-negative breast carcinoma (4 papers, 2018 to 2024). An invasive breast carcinoma which is negative for expression of estrogen receptor (ER), progesterone receptor (PR), and human epidermal growth factor receptor 2 (HER2). "The therapeutic potential of these citrate-AuNPs was evaluated on IFN-γ-induced SOCS1 expression on triple-negative breast cancer cells MDA-MB-231." (PMID 37720228, 2023). "The data indicate that chemically synthesized citrate-AuNPs suppress the expression of SOCS1 by modulating hsa-miR155-5p and deactivating the activity of NF-κB p65/p50 in triple-negative breast cancer cells." (PMID 37720228, 2023). "FOXC1 inhibited P65 degradation by increasing expression of PIN1 (a peptidyl-prolyl isomerase) and reducing expression of SOCS1 (suppressor of cytokine signaling 1) in triple negative breast cancer cells." (PMID 29552326, 2018). "However, the role of SOCS1 in triple-negative breast cancer (TNBC) patients remains poorly explored and subject to conflicting interpretations." (PMID 37720228, 2023).
acute kidney injury (3 papers, 2019 to 2025). Sudden and sustained deterioration of the kidney function characterized by decreased glomerular filtration rate, increased serum creatinine or oliguria. "In a mouse model of acute kidney injury (AKI), our findings indicated that IL-18Rα may mediate anti-inflammatory responses through SOCS1 and/or -3 in cisplatin-induced AKI." (PMID 31861496, 2019).
acute lung injury (3 papers, 2016 to 2022). A condition of lung damage that is characterized by bilateral pulmonary infiltrates (pulmonary edema) rich in neutrophils, and in the absence of clinical heart failure. "Our recent report indicates that the SOCS-1 expression is associated with IL-6 mediated cytoprotection against hyperoxic acute lung injury (HALI) and the mechanism involves SOCS-1- induced ASK-1 degradation." (PMID 27058411, 2016).
allergic asthma (3 papers, 2011 to 2021). A asthma with a basis in a pathological type I hypersensitivity reaction. "Subsequently, we found that Rhy-SLNs relieved allergic asthma via the upregulation of the suppressor of cytokine signaling 1 by repressing the p38 signaling pathway." (PMID 34629023, 2021). "Complications like severe bacterial pneumonia, organizing pneumonia and allergic asthma may point towards a role of SOCS1 in local immunity, e.g. in lung tissue." (PMID 34421895, 2021).
Alzheimer disease (3 papers, 2021 to 2025). A progressive, neurodegenerative disease characterized by loss of function and death of nerve cells in several areas of the brain leading to loss of cognitive function such as memory and language. "Thus, SOCS1 may be a key therapeutic modulator in Alzheimer’s disease." (PMID 33941241, 2021). "We applied our computational framework to prioritize novel putative target genes for Alzheimer’s disease and successfully identified key genes that may serve as novel therapeutic targets (e.g., DLG4, EGFR, RAC1, SYK, PTK2B, SOCS1)." (PMID 33941241, 2021).
apical periodontitis (3 papers, 2018 to 2025). "Polymorphisms in the NOS2 and SOCS1 genes influenced the OHRQoL of patients undergoing root canal treatment in teeth with asymptomatic periapical periodontitis." (PMID 38537022, 2024). "Therefore, in this study, we evaluated whether genetic polymorphisms in IL1A, IL10, IL1RN, NOS2, and SOCS1 genes are potential biomarkers for OHRQoL in patients undergoing root canal treatment in teeth with asymptomatic periapical periodontitis." (PMID 38537022, 2024).
autoimmune encephalitis (3 papers, 2020 to 2025). Inflammation of the brain secondary to an immune response triggered by the body itself. "We describe a family with a heterozygous SOCS1 variant, highlighting neurological manifestations such as MS, autoimmune encephalitis, and recurrent complex regional pain syndrome as novel features." (PMID 41249727, 2025). "Inhibiting miR-155 expression in noninfectious challenges such as stroke, brain trauma, and experimental autoimmune encephalitis decreases brain inflammation, possibly via SOCS1 and SHIP-1." (PMID 32878636, 2020).
colorectal tumors (3 papers, 2017 to 2022). "SOCS1 suppressed metastatic progression of colorectal tumors by preventing the mesenchymal–epithelial transition (MET)." (PMID 35184640, 2022). "SOCS1 expression exhibits a correlation with the clinical stages of colorectal tumors." (PMID 28228755, 2017). "Thus, SOCS1 can be regarded as a molecular marker of the disease progression of colorectal tumors." (PMID 28228755, 2017). "Furthermore, SOCS1 inhibits the invasion and migration of colorectal tumors by preventing the epithelial–mesenchymal transition and promoting the mesenchymal–epithelial transition by increasing E-cadherin and decreasing ZEB1 observed in cell lines and mouse xenograft models." (PMID 28228755, 2017).
Dengue hemorrhagic fever (3 papers, 2017 to 2022). A serious condition caused by Dengue virus infection. "Another example of SOCS1 suppression was observed in patient developing dengue hemorrhagic fever (DHF) and this suppression is associated with elevated levels of miR-150 in CD14+ monocytes infected with DENV2." (PMID 28555130, 2017). "Previous reports have shown that suppression of SOCS1 is correlated with increased miR-150 expression level in DHF (Dengue hemorrhagic fever) patients." (PMID 35891465, 2022).
eosinophilia (3 papers, 2016 to 2025). "Upon OVA sensitization and OVA aerosol challenge, Socs1−/−MGLtg mice showed increased airway eosinophilia (21.5 × 104 cells/ml in BALF) as compared to Socs1+/−MGLtg control mice (7.3 × 104 cells/ml in BALF)." (PMID 27917175, 2016). "Socs1 gene expression was significantly lower expressed in the airways of severe asthmatics compared with mild/moderate asthmatics, and was inversely associated with airway eosinophilia, suggesting that the absence of SOCS1 leads to Th2 bias." (PMID 27917175, 2016).
fungal infection (3 papers, 2015 to 2025). "Although the question of how SOCS1-silenced DCs regulate other types of immune cells needs to be explored further, we speculate that SOCS1-silenced DCs favor the clearance of C. albicans and provide protective immunity against fungal infections." (PMID 25381480, 2015). "The analysis of the M1/M2 (NOS2/ARG1 and SOCS3/SOCS1) ratios expressed by A/J and B10.A cells demonstrates that curdlan increases but laminarin decreases the M1/M2 ratios of A/J macrophages induced by fungal infection." (PMID 26388856, 2015). "The responses of IL-6 and TNF-β consist of up-regulation in the presence of C. albicans, but this is not specific to SOCS1 silencing, suggesting that these cytokines are not regulated by the SOCS1 gene in fungal infections." (PMID 25381480, 2015).
heart failure (3 papers, 2017 to 2024). Inability of the heart to pump blood at an adequate rate to meet tissue metabolic requirements. "In all CHF patients, higher TNF, IL-10, SOCS1 and SOCS3 gene expression was associated with severity of heart failure according to MR-proANP (r = 0.4, p < 0.03, r = 0.39, p < 0.03, r = 0.45, p < 0.03 and r = 0.45, p < 0.02, respectively)." (PMID 38337428, 2024). "In an inflammatory-related context during I/R injury, increased levels of miR-155 were found to lead to the downregulation of its direct target, the suppressor of cytokines signaling 1 (SOCS-1), whose aberrant regulation contributed to the progression from hypertrophy to heart failure." (PMID 32575472, 2020). "SOCS1 DNA administration prevents progression to heart failure." (PMID 28915645, 2017).
HIV-1 infection (3 papers, 2015 to 2017). The type species of lentivirus and the etiologic agent of acquired immunodeficiency syndrome (AIDS). "To this end we investigated the effect of HIV-1 Tat protein on the expression of TLR4 and of SOCS1, a protein associated with HIV-1 infection and disease progression." (PMID 26090662, 2015). "For this, mo-DCs from 6 ART naive patients in advanced stage of HIV-1 infection (mean CD4+ T-cell counts: 225 ± 37) were treated with either siRNA to silence the expression of SOCS-1 gene or scrambled non-silencing RNA following LPS-stimulation for 48 hours." (PMID 26492336, 2015).
liver cirrhosis (3 papers, 2010 to 2022). "As HCV infection may lead to liver cirrhosis, more studies are required to ascertain this pathological link between HCV infection, SOCS1 methylation and HCC progression." (PMID 24635883, 2014).
lymph node metastasis (3 papers, 2017 to 2018). "Moreover, specimens from cases with lymph node metastasis showed significantly reduced SOCS1 staining and concomitant increase in MET and p21 expression." (PMID 28235401, 2017). "SOCS-1 hypermethylation is significantly correlated with lymph node metastasis and TNM stage." (PMID 28915645, 2017).
pancreatic ductal adenocarcinoma (3 papers, 2003 to 2025). An infiltrating adenocarcinoma that arises from the epithelial cells of the pancreas. "Thirteen of 60 pancreatic ductal adenocarcinomas (21.7%) and two of 34 intraductal papillary mucinous neoplasms (IPMNs) (5.9%) had methylated SOCS-1." (PMID 12865927, 2003). "Methylation of CpG island of SOCS-1 gene appears to occur late in the development of pancreatic ductal adenocarcinoma." (PMID 12865927, 2003). "Thirteen of 60 (21.7%) resected primary pancreatic ductal adenocarcinomas showed SOCS-1 CpG island methylation." (PMID 12865927, 2003). "Moreover, the oncogenic miR‐155 is associated to JAK/STAT pathway, downregulating suppressor gene SOCS1, resulting in invasion and migration fo pancreatic ductal adenocarcinoma cell." (PMID 39855897, 2025). "This suggests that, just as is true for usual ductal pancreatic adenocarcinoma, aberrant methylation of SOCS-1 gene may occur late in the development of IPMNs." (PMID 12865927, 2003).
pancreatitis (3 papers, 2018 to 2023). Inflammation of the pancreas. "The vaccine-induced protection against multiple CVB serotypes in the Balb/c, NOD, and suppressor of cytokine signaling-1 (SOCS-1) transgenic mice models, preventing CVB3-induced myocarditis and pancreatitis with no mortalities, as well as preventing CVB1- and CVB4-induced T1D." (PMID 36851152, 2023).
primary biliary cholangitis (3 papers, 2017 to 2021). Primary biliary cholangitis (PBC) is a chronic and slowly progressive cholestatic liver disease of autoimmune etiology characterized by injury of the intrahepatic bile ducts that may eventually lead to liver failure. "In primary biliary cholangitis (PBC), hepatic expression of SOCS1 is inhibited by microRNA-155, which may result in the increased production of proinflammatory cytokines such as tumor necrosis factor α (TNFα) and interleukin 1β (IL-1β)." (PMID 31717271, 2019). "In light of the presented findings, we conclude that inadequate VDR signaling in primary biliary cholangitis with subsequent, miRNA155-modulated SOCS1 expression may lead to the insufficient negative feedback regulation of cytokine signaling." (PMID 28146070, 2017).
retinitis (3 papers, 2019 to 2024). Inflammation of the retina. "Herein we review how SOCS1 and SOCS3 impact the virologic, immunologic, and/or pathologic outcomes of herpesvirus infection with particular emphasis on retinitis caused by HCMV or its mouse model experimental counterpart, murine cytomegalovirus (MCMV)." (PMID 31031749, 2019). "If overexpression of SOCS1 and/or SOCS3 reduces retinitis severity, SOCS1 and/or SOCS3 mimetic peptides or overexpression treatment strategies could be efficacious against this disease, as with experimental autoimmune uveitis (EAU)." (PMID 31031749, 2019). "In addition to these in vitro models, we have observed in our laboratory that after intraocular (subretinal) MCMV inoculation of immunocompromised mice during experimental MCMV retinitis, SOCS1 and SOCS3 mRNA and protein are upregulated in retinitis-susceptible eyes." (PMID 31031749, 2019). "In a mouse model of experimental MCMV retinitis in the late-stage MAIDS, SOCS1 and SOCS3 were abundantly produced by macrophages, granulocytes, microglia, and Müller cells, suggesting their contribution to the severity of retinitis." (PMID 39066272, 2024). "In comparison with the MCMV-infected eyes of animals immunosuppressed by LP-BM5 murine retrovirus infection, SOCS1 and SOCS3 were only moderately stimulated during less severe retinitis development within the MCMV-infected eyes of mice immunosuppressed by corticosteroid treatment." (PMID 34358000, 2021). "Furthermore, there is a decreased intraocular stimulation of SOCS1 and SOCS3 during experimental MCMV retinitis during corticosteroid-induced immune suppression that correlates with reduced severity of retinitis." (PMID 31031749, 2019). "In addition, SOCS1 and SOCS3 are highly stimulated following MCMV infection in retinitis-susceptible MAIDS-10 eyes, but not MCMV infected retinitis-resistant MAIDS-4 eyes." (PMID 31031749, 2019). "Importantly, SOCS1 and SOCS3 are highly stimulated following subretinal MCMV infection in the retinitis-susceptible eyes of MAIDS-10 mice, but not in the MCMV-infected retinitis-resistant eyes of MAIDS-4 mice." (PMID 31031749, 2019). "SOCS1 and SOCS3 were not stimulated, and the severity of retinitis was reduced in the mouse model of experimental MCMV retinitis during corticosteroid-induced immunosuppression." (PMID 39066272, 2024). "Initial studies revealed that SOCS1 and SOCS3 (but not SOCS5) mRNA and protein were remarkably stimulated within the MCMV-infected eyes of MAIDS-10 mice during retinitis development." (PMID 34358000, 2021).
skin inflammatory diseases (3 papers, 2022 to 2024). "The SOCS protein family, in particular, contains eight members that include SOCS1 to SOCS7 and cytokine-inducible SH2-containing protein (CIS), which are known to be implicated in many immunologic-related pathologies as well as inflammatory diseases including skin inflammatory diseases." (PMID 38534350, 2024). "SOCS1 and SOCS3 are the most well-characterized SOCS members in skin inflammatory diseases, where their inhibitory activity on cytokine activated JAKs and consequent anti-inflammatory action has been widely investigated in epidermal keratinocytes." (PMID 38975347, 2024). "In the following section, we discussed the three major SOCS proteins, namely SOCS1, SOCS3, and SOCS5, involved in the pathophysiology of AD and other inflammatory skin disorders." (PMID 35889539, 2022). "Taken together, these data indicate that SOCS1 and SOCS3 proteins may protect against the harmful and prolonged activity of inflammatory cytokines through JAK/STAT signaling in inflammatory skin diseases." (PMID 38534350, 2024).
Stroke (3 papers, 2020 to 2025). Sudden impairment of blood flow to a part of the brain due to occlusion or rupture of an artery to the brain. "This offers a promising therapeutic strategy for IS, through modulation of uncontrolled inflammation in stroke-injured astrocytes by targeting the suppressor of cytokine signaling (SOCS-1) and M1-microglia." (PMID 40362186, 2025). "In one study, injection of an miR-155 inhibitor (anti-miR-155 miRCURY LNATM, Product# 4101082-001, Exiqon) in stroke-induced mice showed significant decrease in cytokines profiles that were correlated with increased expression of miR-155 targets SOCS1 and SHIP1." (PMID 40362186, 2025).
abscess (2 papers, 2021 to 2025). An inflammatory process characterized by the accumulation of pus within a newly formed tissue cavity which is the result of a bacterial, fungal, or parasitic infection or the presence of a foreign body. "If SOCS-1 regulates the expression of collagen and fibrinolytic proteins involved in abscess capsule formation remains to be determined." (PMID 33690673, 2021). "Interestingly, SOCS-1 inhibition mimicked several aspects of the protective effects of IFNγ such as a highly organized and compact abscess with a thick capsule." (PMID 33690673, 2021).